PPFIA1 (PPFI scaffold protein A1)
Description:
May regulate the disassembly of focal adhesions. May localize receptor-like tyrosine phosphatases type 2A at specific sites on the plasma membrane, possibly regulating their interaction with the extracellular environment and their association with substrates.
Synonyms: LIP1; LIP.1; LIPRIN
Tractability: PROTAC: ubiquitination databases record sites on it; its protein half-life has been measured.
Gene: Protein-coding gene on chromosome 11 (70,270,655 to 70,385,312, forward strand). Ensembl gene ENSG00000131626.
Subcellular location: Cytoplasm, cell cortex; Cytoplasm
Subcellular location (Human Protein Atlas): Cytosol; Focal adhesion sites
Pathways (Reactome):
Neuronal System: Acetylcholine Neurotransmitter Release Cycle; Dopamine Neurotransmitter Release Cycle; Glutamate Neurotransmitter Release Cycle; Norepinephrine Neurotransmitter Release Cycle; Receptor-type tyrosine-protein phosphatases; Serotonin Neurotransmitter Release Cycle
Gene Ontology:
Molecular function: protein binding; PDZ domain binding
Biological process: cortical microtubule organization; negative regulation of protein localization to plasma membrane; negative regulation of stress fiber assembly; cell-matrix adhesion; establishment or maintenance of cell polarity; signal transduction; synapse organization; positive regulation of AMPA glutamate receptor clustering; regulation of postsynaptic membrane neurotransmitter receptor levels
Cellular component: cell cortex; cytosol; focal adhesion; cytoplasm; microtubule associated complex; presynaptic active zone; axon; dendrite; growth cone; protein-containing complex; Schaffer collateral - CA1 synapse; spine apparatus
Genetic constraint (gnomAD): Loss-of-function variants: 22 observed, 140.39 expected, observed/expected ratio (o/e) 0.16, 90% interval 0.11 to 0.22. The upper end of that interval is the gene's LOEUF score, 0.22, which puts it in group 1 of 6, group 1 being the genes least tolerant of losing a copy. Missense variants: 1,329 observed, 1,531.5 expected, observed/expected ratio (o/e) 0.87, 90% interval 0.83 to 0.91. Synonymous variants: 540 observed, 565.62 expected, observed/expected ratio (o/e) 0.95, 90% interval 0.89 to 1.02.
Homologues: Orthologues: chimpanzee PPFIA1 (99% identical), macaque PPFIA1 (99% identical), rat Ppfia1 (96% identical), mouse Ppfia1 (96% identical), guinea pig PPFIA1 (96% identical), dog PPFIA1 (94% identical), pig PPFIA1 (94% identical), tropical clawed frog ppfia1 (88% identical), Drosophila melanogaster Liprin-alpha (53% identical), zebrafish ppfia1 (34% identical). Paralogues in human: PPFIA2 (70% identical), PPFIA4 (66% identical), PPFIA3 (63% identical), PPFIBP1 (20% identical), PPFIBP2 (18% identical).
Diseases named in the same sentence as PPFIA1 in open-access papers:
PPFIA1 is named in the same sentence as 34 diseases in open-access papers, as found by Europe PMC text mining. Sharing a sentence is not in itself a finding about the gene and the disease. The quoted sentences say what the papers report.
breast carcinoma (11 papers, 2010 to 2023). "Patients with high PPFIA1 expression were associated with high risk of recurrence, distant metastasis and death from breast cancer (P < 0.05)." (PMID 32410585, 2020). "Another important finding of this study is that high PPFIA1 expression is associated with short survival within luminal breast cancer subtype." (PMID 32410585, 2020). "This study of a well-characterised cohort of clinically annotated patients with early luminal breast cancer demonstrates that high PPFIA1 expression associates with aggressive clinicopathological parameters." (PMID 32410585, 2020). "FADD, TMEM16A, and PPFIA1 gene expressions as a whole were associated with disease-free survival in breast cancer." (PMID 24886289, 2014). "In the breast cancer, PPFIA1 is coamplified with CCND1, which is significantly associated with high-grade phenotype but not tumor stage or nodal stage." (PMID 22920630, 2012). "In addition, upregulation of PPFIA1 expression indicate higher risk of metastasis relapse in breast cancer patients, specifically in estrogen positive and nodal negative group." (PMID 34654889, 2021). "PPFIA1 encoding liprin-α1 shows high correlation between copy number and gene expression in different cancer types and is related to metastatic potential and cell invasive growth in breast carcinoma." (PMID 30005669, 2018). "We further discovered that PPFIA1 can be applied for the prognostic assessment of breast cancer, ovarian cancer, lung cancer and gastric cancer by online Kaplan–Meier Plotter." (PMID 37158817, 2023). "A recent study showed that the expression of PPFIA1 is closely related to poor response to endocrine treatment in luminal breast cancer." (PMID 37158817, 2023). "High expression of PPFIA1 has been demonstrated in several cancers, including breast cancer, head and neck squamous cell carcinomas, and oropharyngeal carcinomas 20-28." (PMID 36605492, 2023). "PPFIA1 upregulation has been shown in 20% of breast cancers, and PPFIA1 was found to serve as an essential promoter in cancer cell migration and invasion." (PMID 34094943, 2021). "Across several cancers, PPFIA1 is overexpressed in carcinomas including those of the head and neck and breast carcinomas." (PMID 34654889, 2021). "Large, well-characterised cohorts of primary luminal breast cancer patients with long-term follow-up was assessed for the clinical impact of PPFIA1 expression at the transcriptomic and proteomic levels." (PMID 32410585, 2020). "This study aims to evaluate the utility of PPFIA1 expression in the luminal breast cancer as a prognostic marker to predict the response to endocrine therapy." (PMID 32410585, 2020). "PPFIA1 is located at the 11q13 amplification region, and is amplified in about 20% of breast cancer." (PMID 32410585, 2020). "CCND1 is the important driver gene of the 11q13 amplicon, and PPFIA1 amplification was found in all CCND1-amplified breast cancers." (PMID 32410585, 2020). "Our findings establish an important role for PPFIA1 expression in luminal breast cancer and response to endocrine therapy." (PMID 32410585, 2020). "PPFIA1 is frequently amplified in breast cancer, and recent functional studies indicate that PPFIA1 is an important promoter of migration and invasion in breast cancer." (PMID 32410585, 2020). "In the current study, we found a correlation between PPFIA1 mRNA expression and integrin family members in luminal breast cancer." (PMID 32410585, 2020). "PPFIA1 expression was assessed at the transcriptomic and proteomic levels utilising large and well-characterised annotated cohorts of luminal breast cancer." (PMID 32410585, 2020). "Transcriptome profiling and Gene Set Enrichment Analysis from HNSCC and breast cancer cells were used to identify expression changes relevant to specific cellular localizations, biological processes and signaling pathways after PPFIA1 knockdown." (PMID 30005669, 2018).
breast carcinoma (continued). "PPFIA1 maps next to CTTN, which encodes for cortactin, and they are co-amplified in 20–30% of HNSCC1, 2 and 10–20% of breast cancer cells." (PMID 27075696, 2016). "PPFIA1 is amplified in human breast cancers and promotes invasiveness of breast and cervical cancer cells." (PMID 24886289, 2014). "In summary, we screened TMEM16A, FADD, and PPFIA1 expression in breast cancer and found that combination of the three gene expressions was associated with disease-free survival in invasive ductal carcinoma of the breast." (PMID 24886289, 2014). "This study provides evidence for the role of PPFIA1 expression in luminal breast cancer." (PMID 32410585, 2020). "High expression of PPFIA1 has been reported in various cancers including breast cancer." (PMID 32410585, 2020). "This is consistent with a previous study where association of PPFIA1 amplification with poor survival was only observed in the subset of ER+ cancers with no prognostic effect on ER negative or HER2+ breast cancer subtypes." (PMID 32410585, 2020). "Altogether, these findings suggest that PPFIA1 could potentially act as in regulating CD82 expression and integrin signalling causing tumour progression and invasion in luminal breast cancer." (PMID 32410585, 2020). "Indeed, our results demonstrate the clinical role of PPFIA1 expression at both transcriptomic and proteomic levels in predicting the recurrence and distant metastasis within luminal breast cancer." (PMID 32410585, 2020). "It is therefore possible that transcriptional induction of PPFIA1 by Snail1 may contribute to the invasive phenotype of breast cancer cells and the induction of vimentin intermediate filament assembly, a hallmark of EMT." (PMID 29729076, 2018). "PPFIA1 is located at the 11q13 region, which is one of the most commonly amplified regions in several epithelial cancers including head and neck squamous cell carcinoma and breast carcinoma." (PMID 27075696, 2016). "Furthermore, in highly invasive breast cancer cells as well as HNSCC cells originating from metastasis or primary persistent as well as primary tumor with PPFIA1 amplification, liprin-α1 expression correlated with growth properties of the cells." (PMID 27075696, 2016). "PPFIA1 is required for the migration and invasion of breast cancer cell lines." (PMID 24886289, 2014). "In support of this data, PPFIA1 has been reported to be a novel Snail1 target, which suggests that positive regulation of PPFIA1 expression by Snail1 may contribute to the invasive phenotype of breast cancer cells." (PMID 34654889, 2021). "Interestingly, in The Cancer Genome Atlas data PPFIA1 alteration was identified in 189 (36%) of 528 sequenced head and neck squamous cell carcinoma patients, whereas in breast cancer data set PPFIA1 amplification was identified in 439 (17%) of 2509 sequenced patients." (PMID 30005669, 2018). "Due to our results showing the association between liprin-α1 and CD82, we explored the significance of PPFIA1 amplification in survival of clinical HNSCC and breast cancer patients from The Cancer Genome Atlas (TCGA) data." (PMID 30005669, 2018). "Clinical data emphasizes the importance of PPFIA1 amplification in cancer cell progression, and as a potential prognostic marker for HNSCC and breast cancer." (PMID 30005669, 2018). "In this study, a positive correlation was observed between PPFIA1 and PPFIBPI in patients with luminal breast cancer, which may confirm their regulatory roles in the migration of tumour cells." (PMID 32410585, 2020). "PPFIA1 is located at the 11q13 amplification region which is related to poor prognosis of the patients in several cancers, including head and neck squamous cell carcinoma (HNSCC) and breast cancer." (PMID 30005669, 2018). "Therefore, we next explored how PPFIA1 amplification influences the survival of the patients from HNSCC and breast cancer in clinical data." (PMID 30005669, 2018).
breast carcinoma (continued). "However, as far as we know, prognostic significance of PPFIA1 expression in breast cancer has not been evaluated to date." (PMID 24886289, 2014). "Survival data showed shorter survival for patients with PPFIA1 amplification when compared to patients with no alteration in both the HNSCC (35.81 versus 64.78 months, p = 0.0152) and breast cancer data (125.3 versus 164.3 months, p = 0.00998) (cbioportal, TCGA-data)." (PMID 30005669, 2018). "In addition to PPFIA1, significance of TMEM16A expression in breast cancer has not been studied to date." (PMID 24886289, 2014).
head and neck squamous cell carcinoma (8 papers, 2014 to 2023). A squamous cell carcinoma that arises from any of the following anatomic sites: lip and oral cavity, nasal cavity, paranasal sinuses, pharynx, larynx, and salivary glands. "Previous studies show a contradictory role of PPFIA1 in regards to the invasiveness of tumour cells, where silencing of PPFIA1 affects the regulation of dynamic events associated with tumour cells invasion whereas the effect is opposite in head and neck squamous cell carcinoma." (PMID 32410585, 2020). "When expression of PPFIA1 was reduced, invasiveness of head and neck squamous cell carcinomas (HNSCC) was found to increase." (PMID 24886289, 2014). "In addition, in the 11q13.3 region of focal gain, the PPFIA1 gene has not been studied extensively in ESCC but was shown to be significantly overexpressed in head and neck squamous cell carcinoma." (PMID 32252688, 2020).
colon carcinoma (3 papers, 2010 to 2023). "Here, we found that two circPPFIA1s (circPPFIA1-L and -S), generated from the exons of PPFIA1, are downregulated in liver metastatic colon cancer cells and tissues." (PMID 36224588, 2022).
oral squamous cell carcinoma (3 papers, 2010 to 2019). "The amplification of 11q13 region, where PPFIA1 is located, is associated to the presence of metastases also in oral squamous cell carcinoma (OSCC)." (PMID 30005669, 2018). "A similar correlation has been reported for cell lines from oral squamous cell carcinoma (TPCN2, CCND1, ORAOV1, ANO1, FADD, PPFIA1 and EMS1; FADD, PPFIA1 and EMS1)." (PMID 20664600, 2010).
esophageal cancer (2 papers, 2021 to 2023). A primary or metastatic malignant neoplasm involving the esophagus. "Oncomine, Gene Expression Profiling Interactive Analysis (GEPIA), and Gene Expression Omnibus (GEO) were used to investigate PPFIA1 expression in esophageal cancer." (PMID 37158817, 2023).
leukemia (2 papers, 2019 to 2021). A malignant (clonal) hematologic disorder, involving hematopoietic stem cells and characterized by the presence of primitive or atypical myeloid or lymphoid cells in the bone marrow and the blood. "Recent findings in K562 leukemia cells have shown that PPFIA1 is a direct target of miRNA-181a, whose downregulation is associated with poor response in leukemia." (PMID 34654889, 2021). "The approach used in this study both enabled us to gain biological insight into the role of PPFIA1 in CML and laid the foundation for a future siRNA-based therapeutic approach targeting PPFIA1 in a subpopulation of leukemia cells." (PMID 30825668, 2019). "Therefore, we hypothesized that PPFIA1 contributes to leukemia growth through an axis involving PARP1, P65, and KIT." (PMID 30825668, 2019).
breast tumour (1 paper, 2020). "In line with our finding, silencing of PPFIA1 was found to upregulate the CD82 cell surface protein in breast tumours." (PMID 32410585, 2020). "Altogether, these findings suggesting a potential role for PPFIA1 expression in the invasive process within breast tumour cells." (PMID 32410585, 2020). "PPFIA1 is located at the 11q13 amplification region, which occurs in about 20% of breast tumours." (PMID 32410585, 2020).
epilepsy (1 paper, 2018). A brain disorder characterized by episodes of abnormally increased neuronal discharge resulting in transient episodes of sensory or motor neurological dysfunction, or psychic dysfunction. "Moreover, PTPRM, PPFIA1, SLC1A2, and SGCE were confirmed to be associated with epilepsy, while PTPRD, ASB5, and MCU were involved in neurological disorders." (PMID 29568349, 2018).
gastric cancer (1 paper, 2023). A primary or metastatic malignant neoplasm involving the stomach. "In view of the high expression of PPFIA1 mRNA in a variety of malignancies, including breast, ovarian, lung, and gastric cancers, we further investigated the prognostic value of PPFIA1 through the Kaplan–Meier Plotter website." (PMID 37158817, 2023).
head and neck cancer (1 paper, 2014). A primary or metastatic malignant neoplasm affecting the head and neck. "A significant number of genes were amplified in greater than 30 percent of cancer patients, including DCUN1D1 (43% of lung squamous cancers), FADD and PPFIA1 (∼30% of head and neck cancers), and PRKCI (36% of lung squamous cancers)." (PMID 24874471, 2014).
invasive breast carcinoma (1 paper, 2023). A carcinoma that infiltrates the breast parenchyma. "explored the prognostic value of PPFIA1 alone or in combination with TMEM16A and FADD in patients with invasive breast cancer and found that combined expression was significantly associated with perineural invasion and a low disease-free survival rate." (PMID 37158817, 2023).
invasive ductal carcinoma (1 paper, 2014). "As a result, we found that FADD expression was associated with T stage, showed a combined score of TMEM16A, FADD, and PPFIA1 expressions and was associated with perineural invasion and disease-free survival in the invasive ductal carcinoma cases." (PMID 24886289, 2014). "In the current study, we screened the expressions of TMEM16A, FADD, and PPFIA1 in invasive ductal carcinoma of the breast." (PMID 24886289, 2014). "Therefore, we screened expressions of FADD and closely located genes (PPFIA1 and TMEM16A) and evaluated the expressions to find clinical significance in invasive ductal carcinoma of the breast." (PMID 24886289, 2014).
lymph node metastasis (1 paper, 2023). "In the GSE53625 dataset, age, histological grade, lymph node metastasis, adjuvant therapy and PPFIA1 expression were significantly related to OS." (PMID 37158817, 2023). "Moreover, age, tumor size, histological grade, tumor invasion depth, lymph node metastasis, and PPFIA1 expression were significantly related to OS in the TMA dataset." (PMID 37158817, 2023). "In the cDNA array dataset, lymph node metastasis, M status, TNM stage and PPFIA1 expression were related to OS." (PMID 37158817, 2023).
metastatic melanoma (1 paper, 2010). A melanoma that has spread from its primary site to another anatomic site. "For example, LIPRIN (PPFIA1), a gene known to enhance cell matrix interaction, and Contractin (CTTN), a gene implicated in squamous cell carcinoma migration and metastasis, were both recurrently amplified in metastatic melanoma." (PMID 20520718, 2010).
psoriatic arthritis (1 paper, 2009). Joint inflammation associated with psoriasis. "Up regulation of human PPFIA1 (LIPRIN) gene in peripheral blood is associated with psoriatic arthritis." (PMID 19624813, 2009).
uterine corpus endometrial carcinoma (1 paper, 2025). A endometrial carcinoma (disease) that involves the body of uterus. "SNV frequency is 41 in uterine corpus endometrial carcinoma (UCEC) and 42 in SKCM for LRP5, and 44 for PPFIA1 in UCEC." (PMID 40478912, 2025).